ZNF572 (zinc finger protein 572)
Description:
May be involved in transcriptional regulation.
Synonyms: FLJ38002
Tractability: PROTAC: UniProt records ubiquitination sites on it; ubiquitination databases record sites on it.
Gene: Protein-coding gene on chromosome 8 (124,973,265 to 124,979,389, forward strand). Ensembl gene ENSG00000180938.
Subcellular location: Nucleus
Subcellular location (Human Protein Atlas): Nuclear speckles
Gene Ontology:
Molecular function: identical protein binding; protein binding; DNA-binding transcription repressor activity, RNA polymerase II-specific; RNA polymerase II cis-regulatory region sequence-specific DNA binding
Biological process: negative regulation of transcription by RNA polymerase II; regulation of cytokine production; regulation of immune system process
Cellular component: nucleus; nucleoplasm
Genetic constraint (gnomAD): Loss-of-function variants: 2 observed, 3.92 expected, observed/expected ratio (o/e) 0.51, 90% interval 0.21 to 1.52. That is too few expected variants to judge how well the gene tolerates losing a copy. Missense variants: 581 observed, 664.46 expected, observed/expected ratio (o/e) 0.87, 90% interval 0.82 to 0.94. Synonymous variants: 187 observed, 216.29 expected, observed/expected ratio (o/e) 0.86, 90% interval 0.77 to 0.98.
Homologues: Orthologues: chimpanzee ZNF572 (98% identical), macaque ZNF572 (97% identical), dog ZNF572 (83% identical), rabbit ZNF572 (78% identical), guinea pig ZNF572 (77% identical). Paralogues in human: ZKSCAN7 (42% identical), ZNF852 (41% identical), ZNF214 (40% identical), ZNF774 (40% identical), ZNF287 (39% identical), ZNF34 (38% identical), ZNF527 (36% identical), ZNF530 (36% identical), ZNF285 (36% identical), ZNF768 (35% identical), ZNF17 (35% identical), ZNF697 (34% identical), and 38 more.
Diseases named in the same sentence as ZNF572 in open-access papers:
ZNF572 is named in the same sentence as 3 diseases in open-access papers, as found by Europe PMC text mining. Sharing a sentence is not in itself a finding about the gene and the disease. The quoted sentences say what the papers report.
intrahepatic cholestasis (1 paper, 2023). A cholestasis characterized by impairment of the bile flow caused by obstruction located in the liver. "Polymorphic variants of CYLD, GC, MBL2, and ZNF572 genes have been collectively associated with the risk of preterm birth or recurrent late pregnancy loss, while dysregulated expression of CYP8B1 may be responsible for pregnancy intrahepatic cholestasis in mice." (PMID 36768581, 2023).
tumor (1 paper, 2025).
ZNF572 also shares sentences with these, for which no sentence is quoted: dilated cardiomyopathy (1 paper).